PRIMA1 (proline rich membrane anchor 1)
Description:
Required to anchor acetylcholinesterase (ACHE) to the basal lamina of the neuromuscular junction and to the membrane of neuronal synapses in brain. Also able to organize ACHE into tetramers (By similarity).
Synonyms: PRiMA
Tractability: Antibody: UniProt places it where antibodies can reach, with medium confidence; UniProt predicts a signal peptide or a membrane-spanning region; its Gene Ontology location is reachable by antibodies, with medium confidence; the Human Protein Atlas places it where antibodies can reach.
Gene: Protein-coding gene on chromosome 14 (93,718,298 to 93,788,994, reverse strand). Ensembl gene ENSG00000175785.
Subcellular location: Cell membrane; Cell junction; Synapse
Subcellular location (Human Protein Atlas): Plasma membrane; Cytosol; Nucleoli
Gene Ontology:
Cellular component: anchoring junction; plasma membrane; synapse
Genetic constraint (gnomAD): Loss-of-function variants: 6 observed, 11.25 expected, observed/expected ratio (o/e) 0.53, 90% interval 0.29 to 1.05. The synonymous counts are far from expectation, so gnomAD's model fits this gene poorly and the ratio says little. Missense variants: 142 observed, 130.47 expected, observed/expected ratio (o/e) 1.09, 90% interval 0.95 to 1.25. Synonymous variants: 66 observed, 48.94 expected, observed/expected ratio (o/e) 1.35, 90% interval 1.11 to 1.65.
Gene-disease validity (ClinGen):
ClinGen rates the evidence that PRIMA1 causes each of these diseases.
epilepsy (autosomal recessive): Limited. A brain disorder characterized by episodes of abnormally increased neuronal discharge resulting in transient episodes of sensory or motor neurological dysfunction, or psychic dysfunction.
Homologues: Orthologues: chimpanzee PRIMA1 (100% identical), macaque PRIMA1 (98% identical), guinea pig PRIMA1 (95% identical), dog PRIMA1 (92% identical), pig PRIMA1 (92% identical), mouse Prima1 (92% identical), rat Prima1 (91% identical), zebrafish prima1 (48% identical), tropical clawed frog prima1 (47% identical).
Diseases named in the same sentence as PRIMA1 in open-access papers:
PRIMA1 is named in the same sentence as 26 diseases in open-access papers, as found by Europe PMC text mining. Sharing a sentence is not in itself a finding about the gene and the disease. The quoted sentences say what the papers report.
breast carcinoma (10 papers, 2005 to 2025). "We initially showed, in animal models, that PRIMA-1 and APR-246 effectively inhibit the development of tumors in xenografts derived from human breast cancer cells; their activity was bolstered by the concomitant administration of 2aG4, an antibody that targets tumor blood vessels." (PMID 41440212, 2025).
adenoma (5 papers, 2015 to 2021). A neoplasm arising from the epithelium. "Another DNA methylation study specifically evaluated methylation in four genes (SFRP1, SFRP2, SDC2 and PRIMA1), with an AUC of 0.93 for the multi-marker panel for detecting adenoma." (PMID 34503217, 2021). "A set of transcripts (18 genes including MAL, SFRP1, SULT1A1, PRIMA1, PTGDR) showed decreasing expression (p < 0.01) in the biopsy samples along the adenoma-carcinoma sequence." (PMID 26482433, 2015). "No significant gene expression alterations could be detected in the stromal cells isolated from adenomas compared to the normals, but COL1A2, FADS1, MAL, PRIMA1, SULF1, THBS2, TIMP1 genes’ transcripts showed significant differences (p < 0.05) in logFc values for the tumour versus normal comparison." (PMID 26482433, 2015).
ovarian carcinoma (4 papers, 2013 to 2023). A malignant neoplasm originating from the surface ovarian epithelium. "Together, PRIMA-1 and SHetA2 had additive effects and prevented ovarian cancer tumor growth in 67% of mice, indicating that this combination may be effective as a maintenance therapy for ovarian cancer patients." (PMID 36671544, 2023).
atherosclerosis (2 papers, 2012 to 2019). A disease characterized by the build-up of fatty material and calcium deposition in the arterial wall resulting in partial or complete occlusion of the arterial lumen. "Interestingly, Prima1, one of the genes significantly altered, has recently been robustly associated with carotid intima-media thickness in patients with atherosclerosis." (PMID 23284944, 2012). "Importantly, the minor allele of rs7152362 in PRiMA1, which was associated with smaller cIMT, was also associated with fewer atherosclerotic events in the NOMAS cohort, supporting the clinical relevance of the reported genetic associations with subclinical atherosclerosis phenotype." (PMID 31406157, 2019).
myeloma (2 papers, 2014 to 2016). "Thus, it was highly relevant to interrogate if p73 was associated with PRIMA-1-induced-UPR in myeloma." (PMID 27533450, 2016). "The IRE1/XBP1 route was described to be crucial for differentiation and survival of plasma cells, thus, we postulated that PRIMA-1 may be exerting its anti-myeloma role by inhibiting the pro-survival effects of IRE1/XBP1." (PMID 27533450, 2016). "Previously, p73 was identified to be important for PRIMA-1 cytoxicity in myeloma." (PMID 27533450, 2016).
thyroid cancer (2 papers, 2017 to 2022).
colorectal cancer (1 paper, 2015). A primary or metastatic malignant neoplasm that affects the colon or rectum. "Hypermethylation of the selected markers (MAL, PRIMA1, PTGDR and SFRP1) can result in reduced gene expression and may contribute to the formation of colorectal cancer." (PMID 26482433, 2015).
epilepsy (1 paper, 2020). "Further support to the notion that the cholinergic system is crucially implicated in SHE is given by the observation that a recessive form of the epilepsy is associated with mutant proline-rich membrane anchor 1 (PRIMA1), which anchors acetylcholinesterase (AChE) to the synaptic membrane." (PMID 33255633, 2020).
glioma (1 paper, 2024). A benign or malignant brain and spinal cord tumor that arises from glial cells (astrocytes, oligodendrocytes, ependymal cells).
osteosarcoma (1 paper, 2016). A usually aggressive malignant bone-forming mesenchymal neoplasm, predominantly affecting adolescents and young adults.
prostate carcinoma (1 paper, 2014). A carcinoma that arises from epithelial cells of the prostate gland.
tumor (26 papers, 2005 to 2025). "In particular, they reported that NOXA, microRNA-34a, microRNA-29a, MEK (Mitogen-activated protein/extracellular signal-regulated kinase kinase), and c-myc were linked to the anti-tumor effects of PRIMA-1/APR-246." (PMID 29258181, 2017). "This denotes that PRIMA-1's mechanism of action is actually much more diverse than previously thought, underlining its promising role in targeting various tumor suppressor pathways and its versatility in keeping drug resistance at bay." (PMID 27533450, 2016). "APR-246, a methylated form of PRIMA-1, is more active than PRIMA-1 and has a synergistic effect with cisplatin to inhibit the tumor xenograft growth in SCID mice." (PMID 34439241, 2021). "The tumor suppressor effect of PRIMA-1 was related to apoptosis induction, which indeed was abolished in the presence of caspase inhibitors." (PMID 33430525, 2021). "Since this first publication, many studies have reported the tumor suppressor effects of PRIMA-1, then APR-246, in various cancers." (PMID 29258181, 2017). "In addition, the anti-tumor effects of PRIMA-1 and APR-246 appeared mediated by changes in cell cycle progression, with an accumulation of cells in the G0/G1 phase, or in the G2 phase." (PMID 29258181, 2017).
tumor (continued). "PRIMA-1 synergizes with chemotherapeutic drugs to induce tumor cell apoptosis." (PMID 23351152, 2013). "In line with this hypothesis, PRIMA-1 was reported to cooperate with the chemotherapeutic drug cisplatin (that stimulates p73 functions) in inducing tumor cell apoptosis and inhibiting tumor growth in xenografts." (PMID 21391908, 2011). "Three additional genes, BCL2, PRIMA1, and PTGDR showed hypermethylation only in tumour samples." (PMID 26482433, 2015).